TTR (transthyretin)
Diseases named in the same sentence as TTR in open-access papers (continued):
Sharing a sentence is not in itself a finding about the gene and the disease.
cardiomyopathy (182 papers, 2013 to 2026). A disease of the heart muscle or myocardium proper. "Given the established relationships between distinct TTR variants and their associated phenotypes, which can vary from exclusive neuropathy to those overlapping with cardiomyopathy, the penetrance of TTR variants exhibits considerable variability." (PMID 40407311, 2025). "As Thr60Ala and Val122Ile are the commonest TTR variants in the UK and patients often present with cardiomyopathy, early diagnosis of ATTRv‐PN is critical for treatment decisions." (PMID 40580033, 2025). "Reports have demonstrated a progression of cardiomyopathy and neuropathy in numerous patients with non-V30M TTR mutations despite liver transplantation." (PMID 40406766, 2025). "Based on the results of the ATTRibute trial, the FDA approved the clinical use of acoramidis for the treatment of TTR cardiomyopathy (both wildtype and variant) to reduce cardiovascular death and hospitalizations, in late November 2024." (PMID 40943848, 2025). "ATTR amyloidosis is caused by TTR misfolding, leading to the progressive and potentially fatal cardiomyopathy caused by extracellular deposition of transthyretin-derived insoluble amyloid fibrils in the myocardium." (PMID 39199169, 2024). "These included variants in well-known disease loci such as TTR V1221, associated with cardiomyopathy and neuropathy in Black individuals." (PMID 39316441, 2024). "Of interest, cardiomyopathy was frequently reported in the family history of TTR‐mutated patients (57%) but was uncommon in patients themselves (37%)." (PMID 37725003, 2024). "TTR variants are generally associated with later onset cardiomyopathy and neuropathy and increased risk of heart failure." (PMID 38229148, 2024). "Cardiomyopathy caused by aggregation and deposition of transthyretin amyloid fibrils in the heart (ATTR-CM) is divided into a hereditary (ATTRv) and a wild-type (ATTRwt) forms." (PMID 38765770, 2024). "As an additional example highlighting diseases more common in Black individuals, the TTR V122I variant — a variant present in 3%–4% of Black individuals — was associated with cardiomyopathy, sinus node dysfunction, and peripheral neuropathy in our PheWAS." (PMID 39316441, 2024). "TTR‐mutated patients presented a higher frequency of unexplained weight loss (p = 0.007), gastrointestinal symptoms (p = 0.05), and family history of cardiomyopathy (p = 0.05)." (PMID 37725003, 2024). "Recently, we described a novel mutation in the TTR gene (A19D-TTR, now A39D-TTR) in a Brazilian male with German ancestry living in southern Brazil who died from a severe cardiomyopathy." (PMID 38925327, 2024). "Systemic amyloidosis due to accumulation of misfolded transthyretin (TTR) protein causes cardiomyopathy in approximately 50,000 to 150,000 people in the US." (PMID 39540049, 2024). "Data on the type of TTR mutation, presence of cardiomyopathy, treatment, and Body Mass Index (BMI) were collected." (PMID 36846120, 2023). "The majority of TTR variants cause a “neuropathic” or a “mixed” phenotype,4, 5although some variants typically manifest as a predominant or isolated cardiomyopathy." (PMID 37059440, 2023). "Tafamidis reduced death and hospitalizations associated with cardiovascular events in patients with transthyretin-associated cardiomyopathy." (PMID 36902588, 2023). "Heparan sulfate (HS) was detected as a pertinent component in the heart of cardiomyopathy associated with TTR amyloid deposition by immunohistochemical staining." (PMID 36835140, 2023). "ATTR is an autosomal neurodegenerative disease characterized by neuropathy and cardiomyopathy caused by variants in the transthyretin (TTR) gene." (PMID 36982893, 2023).
cardiomyopathy (continued). "This test, minimally invasive, should be performed routinely on all diagnosed patients since there are transthyretin gene mutations that present as late-onset cardiomyopathy." (PMID 36983274, 2023). "Transthyretin amyloid cardiomyopathy (ATTR-CM) is a progressive and fatal cardiomyopathy caused by the extracellular deposition of transthyretin (TTR) amyloid fibrils in the heart, either in its variant or wild-type form." (PMID 36444226, 2022). "Previously, a new dominant TTR mutation was found to be related to sensory and peripheral neuropathy, vitreous opacities, and cardiomyopathy, with an early age of onset of disease." (PMID 36289657, 2022). "V122I, a common pathogenic TTR mutation, is found in 3–4% of individuals of African ancestry in the United States and has been associated with cardiomyopathy and heart failure." (PMID 34079032, 2021). "A large number of BioMe participants are heterozygous for TTR V142I, a common founder variant that is highly prevalent in AA and HL populations and significantly increases the risk for cardiomyopathy and heart failure." (PMID 33546753, 2021). "Aside from the rarity of hereditary ATTR, pathogenic accumulation of wild type TTR fibers in the heart is also observed in patients and has been recognised as a cause for cardiomyopathy and eventual heart failure." (PMID 34539755, 2021). "Of these, 24(62%) patients had a germline mutation of the TTR gene while 15 (38%) had wild type transthyretin cardiomyopathy." (PMID 33068247, 2021). "For individuals 60 years of age or older, we observed significantly increased odds of relevant cardiac phenotypes with P/LP TTR variants, particularly cardiomyopathy, heart failure, and atrial fibrillation." (PMID 34746851, 2021). "Most other amyloidogenic TTR mutations are associated with polyneuropathy in addition to cardiomyopathy, with variable visceral and other tissue involvement." (PMID 34876572, 2021). "On the other hand, in a cohort of TTR wild-type cardiomyopathy patients, the p.Gly26Ser polymorphism was found in 7% of subjects and 12% of healthy controls, prompting the authors to discuss the genetic variant as a protective factor." (PMID 33324896, 2019). "A small pilot study with EGCG administration to human carriers of amyloidogenic TTR mutations including TTR V30M revealed a reduction of myocardial mass in the case of cardiomyopathy, indicating an inhibitory effect of EGCG on TTR amyloid fibril formation." (PMID 30875761, 2019). "It is associated with vegetative dysfunction and cardiomyopathy with a transthyretin (TTR) mutation of the TTR gene and usually occurs in adults during the third decade of life." (PMID 30065914, 2018). "Patients with cardiomyopathy who have wild-type or variant TTR traditionally develop symptoms in their sixties." (PMID 23425518, 2013). "Here we have described a new TTR variant in the Brazilian population, namely A19D, which is associated with severe cardiomyopathy." (PMID 24358189, 2013). "We report the case of a Brazilian patient suffering from a severe cardiomyopathy who carries a rare mutation in exon 2 of the TTR gene that results in an Ala to Asp substitution at position 19 (A19D)." (PMID 24358189, 2013). "Transthyretin cardiac amyloidosis (ATTR-CA), caused either by hereditary transthyretin mutations (ATTRv) or wild-type transthyretin depositions (ATTRwt), is an infiltrative cardiomyopathy marked by progressive diastolic dysfunction, wall thickening, and restrictive filling patterns." (PMID 41226753, 2025). "The most common mutation worldwide, V30M, is caused by a methionine for valine substitution at residue 30 of the mature TTR protein, which is encoded by the TTR gene located on chromosome18q12.1, and could manifest as neuropathy and/or cardiomyopathy." (PMID 40565953, 2025). "Wild-type TTR predominantly causes cardiomyopathy, though it may also manifest as carpal tunnel syndrome." (PMID 41024906, 2025).
cardiomyopathy (continued). "Mutations in the TTR gene can lead to familial transthyretin amyloidosis, which is an autosomal dominant, inherited systemic degenerative disease primarily associated with peripheral neuropathy and/or cardiomyopathy." (PMID 40564999, 2025). "In addition, hereditary ATTRv-CM is associated with more than 110 TTR mutations, where severe progressive axonal polyneuropathy (ATTRv-PN) and cardiomyopathy (ATTRv-CM) are the most prominent manifestations." (PMID 39796004, 2024). "Additionally, wild-type TTR can aggregate in the disease senile systemic amyloidosis, causing cardiomyopathy due to aggregates in the heart." (PMID 35626697, 2022). "Indeed, in the age-stratified subanalysis (≥60 years), we observed a marked increase in the odds of heart disease, including cardiomyopathy, heart failure, and atrial fibrillation, in individuals with P/LP TTR variants." (PMID 34746851, 2021). "Cardiac ATTR amyloidosis, a serious but much under-diagnosed form of cardiomyopathy, is caused by deposition of amyloid fibrils derived from the plasma protein transthyretin (TTR), but its pathogenesis is poorly understood and informative in vivo models have proved elusive." (PMID 34876572, 2021). "Indeed, TTR amyloidogenesis is associated with the development of severe clinical complications including peripheral neuropathy, autonomic dysfunctions, cardiomyopathy, or death in some cases, a condition which is generally referred to as ATTR amyloidosis." (PMID 31835306, 2019). "More than 100 amyloidogenic TTR point mutants are described, of which the TTR Val30Met preferentially gives rise to a sensorimotor amyloidotic polyneuropathy (TTR-FAP), whereas other mutations, such as the Val122Ile, predispose to the development of cardiomyopathy (TTR-FAC)." (PMID 28384285, 2017). "Furthermore, in a large population-based cohort with exome sequencing data, participants with pathogenic or likely pathogenic TTR variants, exhibited a significantly increased odds of heart disease (including heart failure, cardiomyopathy, and atrial fibrillation)." (PMID 39537877, 2025). "Further, mutations in the TTR gene are implicated in the etiology of several diseases, including amyloidotic polyneuropathy, euthyroid hyperthyroxinaemia, amyloidotic vitreous opacities, cardiomyopathy, oculoleptomeningeal amyloidosis, meningocerebrovascular amyloidosis, and carpal tunnel syndrome." (PMID 36566436, 2023). "Advanced conduction abnormalities were present in 72 (9%) patients, and it was a relevant RF for TTR cardiomyopathy (Sp 79%)." (PMID 41574038, 2026). "Sensitivity was very high for each specific aetiology, ranging from 88% for TTR cardiomyopathy to 100% for Friederich’s ataxia." (PMID 41574038, 2026). "Advanced conduction abnormalities were associated with TTR-CA, and extreme right axis deviation was rare in our cohort (2%) but described only in patients with Danon disease and PRKAG2 cardiomyopathy." (PMID 41574038, 2026). "In real-world, wild-type transthyretin cardiomyopathy is increasingly diagnosed in patients ≥ 80 years old (octogenarians), although being underrepresented in randomized clinical trials." (PMID 40036202, 2025). "The accumulation of TTR proteins results in the presentation of the signs and symptoms of cardiomyopathy (CM) and/or polyneuropathy (PN)." (PMID 41002621, 2025). "Although the study was conducted on a small number of patients, it revealed 18 protein level variations unique to hATTR cardiomyopathy, including significantly lower TTR levels in this group." (PMID 40722719, 2025). "Recent trials to evaluate novel therapies to treat transthyretin (ATTR) and associated cardiac amyloidosis and cardiomyopathy." (PMID 39540049, 2024). "The first clinical trial using LNP-encapsulated CRISPR-Cas9 was initiated in 2020 and targeted the TTR gene in hepatocytes for the treatment of transthyretin amyloidosis with cardiomyopathy." (PMID 39256822, 2024).
cardiomyopathy (continued). "Tafamidis, an oral TTR stabilizer for the treatment of wtATTR and hATTR cardiomyopathy, prevents TTR dissociation, thereby attenuating disease progression." (PMID 39336977, 2024). "One of the strongest findings was related to cardiomyopathy, which is a primary Val122Ile outcome due to the accumulation of TTR fibrils in the myocardium." (PMID 38523305, 2024). "All but one patient had tafamidis, a stabilizer of the native tetramer structure of TTR, which was clinically indicated in this series of patients with genetic testing-proven hereditary TTR-cardiomyopathy." (PMID 37256072, 2023). "Mutations that destabilize tetrameric TTR result in familial TTR amyloidosis (ATTR) and lead to earlier onset of amyloid polyneuropathy and cardiomyopathy." (PMID 35724960, 2022). "The disease is characterized by transthyretin (TTR) amyloid fibrils deposition in multiple organs, mostly leading to sensory‐motor neuropathy, autonomic dysfunction, and cardiomyopathy, accompanied by involvement of other organs." (PMID 35665499, 2022). "Results of TTR mutation screening, with red flag symptom, CTS risk factors, and family history of CTS and cardiomyopathy." (PMID 35959393, 2022). "Presently, Tafamidis is the first Food and Drug Administration (FDA) and European Medicines Agency (EMA)-approved targeted treatment for TTR cardiomyopathy (ATTR-CM)." (PMID 35337074, 2022). "Inflammation can accompany various cardiomyopathies and myocarditis, demonstrating the importance of activating an inflammatory response, perhaps directly by the exogenous TTR molecules." (PMID 35262277, 2022). "Incomplete (if not low) penetrance has been a consistent finding in numerous genome-first inherited cardiomyopathy studies, so a similar pattern for TTR is possible." (PMID 34746851, 2021). "A similar observation was recently made with kinetic stabilizer treatment of transthyretin (TTR) cardiomyopathy." (PMID 35757512, 2021). "Aggregation of human wild-type transthyretin (hTTR), a homo-tetrameric plasma protein, leads to acquired senile systemic amyloidosis (SSA), recently recognised as a major cause of cardiomyopathies in 1–3% older adults." (PMID 33311636, 2020). "In patients with ATTR amyloidosis with cardiomyopathy, TTR amyloid infiltrates the myocardium leading to heart wall thickening that impairs both diastolic and systolic function." (PMID 32062791, 2020). "They represented a considerable heterogeneous population in which eight different TTR non-V3OM mutations were observed with mixed neurological and cardiomyopathy presentation." (PMID 31407119, 2019). "It occurs as cardiomyopathy in elderly men with European ancestry, and TTR amyloid fibrils can be found in the hearts of the 25% of elderly individuals over 80 years of age." (PMID 28335735, 2017). "A phase 2, open-label study evaluating the efficacy, tolerability, safety, and pharmacokinetics of doxycycline and TUDCA in TTR-related cardiomyopathy is currently underway." (PMID 26664897, 2015). "At least five clinical trials that investigate tafamidis in patients with TTR-related cardiomyopathy are active or have been completed." (PMID 26664897, 2015). "Inhibition of TTR expression using siRNA therapy is yet another therapeutic approach being tested to treat TTR-related cardiomyopathy (rows 6–7)." (PMID 26664897, 2015). "99mTc-DPD scintigraphy can assist in the differential diagnosis between TTR-related cardiomyopathy and sarcomeric hyptertrophic cardiomyopathy, since only myocardium infiltrated by TTR uptakes the tracer." (PMID 23425518, 2013). "A diagnosis of HCM after age 60 carried a Sp of 86% for TTR cardiomyopathy." (PMID 41574038, 2026). "Perhaps this patient could switch to the other TTR silencer available, as that could help alleviate their signs and symptoms of cardiomyopathy." (PMID 41002621, 2025).
cardiomyopathy (continued). "A comprehensive genetic cardiomyopathy panel was repeated but did not reveal pathogenic variants in the transthyretin gene and he was diagnosed with wild-type ATTR-CA." (PMID 40645707, 2025). "In cardiomyopathy, the deposition of transthyretin (TTR) increased the production of ROS, correlating with left ventricular systolic dysfunction, though likely indirectly from endoplasmic reticulum stress and calcium dyshomeostasis by non-fibrillar TTR species." (PMID 38378578, 2024). "The mutated TTR tetramer dissociates in misfolded monomers that accumulate in tissues such as the heart and peripheral nervous system (PNS), leading, respectively, to cardiomyopathy and progressive axonal peripheral neuropathy." (PMID 36846120, 2023). "However, TTR-related cardiomyopathy in Bulgarian patients is worse than that of the Sicilian cohort, and it seems that the clinical phenotype is strongly influenced by respective geographic area." (PMID 36289657, 2022). "Deposition of TTR in the myocardium results in a restrictive form of cardiomyopathy." (PMID 34017661, 2021). "Our results provide a proof-of-concept for a genome-first approach to the identification of hATTR cardiomyopathy and help to inform the potential inclusion of the TTR gene in recommendations on secondary findings reporting and population-based genomic screening analyses." (PMID 34746851, 2021). "In case of heart failure, 123I-MIBG scintigraphy reflects cardiomyopathy rather than cardiac autonomic neuropathy in ATTRm patients and TTR mutation carriers." (PMID 30374850, 2020). "Late HMR and wash-out rate on 123I-MIBG scintigraphy reflect cardiomyopathy rather than cardiac autonomic neuropathy in ATTRm patients and carriers of a TTR mutation in case of heart failure." (PMID 30374850, 2020). "The precursor protein is transthyretin and presents with a slowly progressive cardiomyopathy." (PMID 31131121, 2019). "In addition, recently, it was found that after liver transplant, some patients develop TTR cardiomyopathy due to deposition of wild-type TTR in their heart." (PMID 30875761, 2019). "Transthyretin (TTR) variants are associated with hereditary amyloidoses, clinically termed familial amyloidotic polyneuropathy (FAP) or cardiomyopathy when point mutations in the TTR gene result in protein deposition in the peripheral nervous system (PNS) or heart, respectively." (PMID 28583160, 2017). "Future studies will determine whether one or both of these agents will have durable inhibitory effects on TTR amyloidotic neuropathy and cardiomyopathy." (PMID 23425518, 2013). "Additionally, in the absence of an early discussion about ATTR-CM, the patient couldn’t know that the tingling she felt was related to TTR cardiomyopathy." (PMID 37950168, 2023). "Furthermore, in individuals found to have a TTR mutation on the basis of bilateral CTS, it would be valuable to determine what proportion of them may already have cardiomyopathy." (PMID 35959393, 2022). "Symptoms of cardiomyopathy were reported in nine of the patients without the TTR mutation." (PMID 35959393, 2022). "We explored the predictive value of some of the major Red Flag symptom for a TTR mutation, such as symptoms of cardiomyopathy, orthostatic hypotension, or GI complaints, and they did not seem to increase the likelihood of a TTR mutation in our African American cohort with bilateral CTS." (PMID 35959393, 2022). "Accordingly, another GalNAc–siRNA conjugate targeting TTR, vutrisiran (ALN-TTRsc02), will be used to further explore the benefit–risk profile of RNAi therapeutics across the full spectrum of ATTR amyloidosis, including patients with hereditary and wt cardiomyopathy." (PMID 32062791, 2020). "Concerning the hereditary forms of the disease, TTR V122I is also a very frequent variant, in particular, in the Black American population, being this variant related with a predominant involvement of the heart, now designated as ATTR amyloidosis with cardiomyopathy." (PMID 30875761, 2019).